TOR3A (torsin family 3 member A)
Synonyms: ADIR; FLJ22345; ADIR2
Tractability: Antibody: UniProt predicts a signal peptide or a membrane-spanning region. PROTAC: ubiquitination databases record sites on it; its protein half-life has been measured.
Gene: Protein-coding gene on chromosome 1 (179,081,854 to 179,098,023, forward strand). Ensembl gene ENSG00000186283.
Subcellular location: Cytoplasm; Endoplasmic reticulum lumen
Gene Ontology:
Molecular function: ATP hydrolysis activity; ATP binding
Cellular component: endoplasmic reticulum; endoplasmic reticulum lumen; extracellular exosome; nuclear envelope; cytoplasm
Genetic constraint (gnomAD): Loss-of-function variants: 39 observed, 36.56 expected, observed/expected ratio (o/e) 1.07, 90% interval 0.82 to 1.39. The upper end of that interval is the gene's LOEUF score, 1.39, which puts it in group 5 of 6, group 1 being the genes least tolerant of losing a copy. Missense variants: 502 observed, 464.61 expected, observed/expected ratio (o/e) 1.08, 90% interval 1 to 1.16. Synonymous variants: 219 observed, 198.19 expected, observed/expected ratio (o/e) 1.11, 90% interval 0.99 to 1.24.
Homologues: Orthologues: chimpanzee TOR3A (99% identical), macaque TOR3A (95% identical), guinea pig TOR3A (76% identical), pig TOR3A (74% identical), dog TOR3A (73% identical), rat Tor3a (69% identical), mouse Tor3a (68% identical), rabbit TOR3A (51% identical), zebrafish tor3a (47% identical), tropical clawed frog tor3a (42% identical), Caenorhabditis elegans ooc-5 (26% identical), Caenorhabditis elegans tor-2 (24% identical), and 2 more. Paralogues in human: TOR1A (33% identical), TOR1B (32% identical), TOR2A (29% identical), TOR4A (18% identical).
Diseases named in the same sentence as TOR3A in open-access papers:
TOR3A is named in the same sentence as 5 diseases in open-access papers, as found by Europe PMC text mining. Sharing a sentence is not in itself a finding about the gene and the disease. The quoted sentences say what the papers report.
dengue (1 paper, 2022). "Of interest, we observed that several predictive genes of severe dengue, including GYG1, TOR3A, SPON2, GRAP2 and GBP2, were also highly transcribed in the ASCs and effector T cells at Day −1 in our dataset." (PMID 35345453, 2022).
infection (1 paper, 2022). The state of being infected such as from the introduction of a foreign agent such as serum, vaccine, antigenic substance or organism. "While the extent and magnitude of gene expression changes were not as robust as the virulent ZIKV-MR766 infection model, we nevertheless saw significant changes in the expression of 7 of 14 genes analyzed, including Adora2, Cacna1e, Ccl5, Gpr84, Nlgn1, Pmch, and Tor3a." (PMID 35462541, 2022).
neurologic disease (1 paper, 2017). "TOR3A (torsin family 3 member A) belongs to a family of genes with a role in neurologic disease, as well as chaperone-like functions." (PMID 28481924, 2017).
TOR3A also shares sentences with these, for which no sentence is quoted: respiratory syncytial virus infection (1 paper); ZIKV infection (1).